FGF1 (fibroblast growth factor 1)
Diseases named in the same sentence as FGF1 in open-access papers (continued):
Sharing a sentence is not in itself a finding about the gene and the disease.
Hyperglycemia (continued). "We conclude that FGF1 exerts its neuroprotective role and normalizing hyperglycemia effect, consequently ameliorates DICD, implying FGF1 holds a great promise to develop a new treatment for DICD." (PMID 32460803, 2020). "Additionally, much of the literature has focused on the long-term effects of FGF1 using diabetic rodent models with disrupted leptin signaling, and much less is known about the mechanisms underlying acute effects of FGF1, which are independent of long-term reductions in hyperglycemia." (PMID 34987476, 2021). "In our current study, however, FGF1 treatment did not increase its motor speed of db/db mice, suggesting that hyperglycemia did not affect motor function." (PMID 32460803, 2020). "Mutant M2 exhibited a less significant hyperglycemia, while the effect upon plasma glucose for mutant M3 was essentially indistinguishable from that of FGF-1+heparin." (PMID 23133616, 2012). "Furthermore, FGF1 can act as an insulin sensitizer to effectively reduce hyperglycemia in diabetes without adverse reactions." (PMID 34025437, 2021). "Additionally, as an insulin sensitization, FGF1 effectively normalizes the hyperglycemia of type 2 diabetes without adverse effects." (PMID 32460803, 2020). "Previous studies demonstrated that direct injection of FGF1 into the ARH is sufficient to reduce hyperglycemia in rodents; however, whether FGF1 acts directly on ARH neurons, which subpopulation of neurons respond to FGF1, and what receptor(s) mediate the effects of FGF1, is unknown." (PMID 34987476, 2021). "Based on this model, we speculate that Mef2c induction by FGF1 contributes to a sustained reduction in the excitability of hypothalamic neurocircuits that raise the BG level when activated, leading to synaptic DCV accumulation and potentially contributing to sustained amelioration of hyperglycemia." (PMID 32895383, 2020). "Thus, it is reasonably speculated that independent of normalizing hyperglycemia, FGF1 may directly exert its neuroprotective role and improve the cognitive function after permeating BBB, which need to be further confirmed in further study." (PMID 32460803, 2020). "When icv FGF1 injection was combined with continuous SHU9119 infusion, however, remission of hyperglycemia was not sustained even though the transient effects of icv FGF1 to reduce food intake, BW, and BG levels remained intact." (PMID 32895383, 2020). "But FGF1-mediated normalizing hyperglycemia may not the only contributed factor for FGF1 treating DICD, which may explain why FGF1 treatment exerts a better neuroprotective role for DICD when comparing with that in metformin treatment group." (PMID 32460803, 2020).
pancreatic cancer (16 papers, 2001 to 2024). "Stimulation of pancreatic cancer cells with PGE2 led to the secretion of fibroblast growth factor 1 (FGF1)." (PMID 37298790, 2023). "Based on data that has attributed cellular functions to fibroblast proliferation in other tissues, we investigated a panel of ten central regulators of cell proliferation (c-Myc, Cyclin D1, Cyclin E1, FGF2, FGFR2, EGFR, EGF, FGF1, FGFR1 and VEGFA) in pancreatic cancer-associated fibroblasts (CAFs)." (PMID 38678032, 2024). "Indeed, in pancreatic cancer cells FGF1/FGFR1 signaling activates AKT pathway leading to GSK-3β phosphorylation and inhibition which finally results in decreased phosphorylation of c-Myc T58 and in reduced c-Myc proteasomal degradation." (PMID 39482742, 2024). "In pancreatic cancer, the disruption of YAP transcriptional activity by Super-TDU suppresses secreted YAP/TEAD target genes implicated in extracellular matrix remodeling, such as AREG, CTGF, CYR61, fibroblast growth factor 1 (FGF1) and mesothelin (MSLN)." (PMID 33467099, 2021). "FGF1 is aberrantly expressed in pancreatic cancer, lung cancer, glioblastoma and prostate cancer." (PMID 32615540, 2020). "Concomitantly, c-Myc S62 phosphorylation was increased upon FGF1-mediated FGFR1 activation leading to c-Myc stabilization and increase of c-Myc levels and pancreatic cancer cell growth." (PMID 39482742, 2024). "In addition, recent studies revealed that FGF1 may promote the amplification and stemness properties of lung and pancreatic cancer cells.Thus, to optimize the applicability and efficiency of FGF1, future studies should aim to, at least minimize these adverse effects." (PMID 35764933, 2022). "Proliferation of pancreatic cancer cells is known to be mediated by PDGF and FGF1 signalling pathways." (PMID 30923340, 2019). "The FGFR1 IIIb induced cell proliferation after FGF‐1, FGF‐2 and FGF‐4 stimulations via production of a glycosylated 110kd protein in pancreatic cancer cells." (PMID 30945363, 2019). "In addition, fibroblast growth factor 1 (FGF1) secreted by CAFs is essential for paracrine MYC activation and protein stability coordinately with pancreatic tumor cell-autonomous signals." (PMID 36230914, 2022). "Interestingly, the pro-angiogenic effect of FGF-1 and FGF-2 besides the VEGF–VEGFR2 axis was already demonstrated and combination of the pan-FGFR inhibitor SSR128129E with DC101 in mouse models of pancreatic cancer yielded an additive therapeutic effect." (PMID 28814715, 2017).
prostate carcinoma (14 papers, 2005 to 2025). A carcinoma that arises from epithelial cells of the prostate gland. "The initiation of fibroblast growth factor 1 (FGF1) expression coincident with the decrease of FGF2 expression is a well-documented event in prostate cancer (PCa) progression." (PMID 38764020, 2024). "Meanwhile, we also observed a significant increase in HSC factors/markers (KITLG, CXCR4 and FGF1) in Tie-2High PC-3 cells when compared to the Tie-2Low population, further suggesting that Tie-2High prostate cancer cells are similar to HSCs." (PMID 25978029, 2016). "For instance, the upregulation of regulatory factors including TGFβ and FGF1 in CdGAP-depleted cells could differentially influence the role of CdGAP in prostate cancer growth in a specific tumor microenvironment." (PMID 34493786, 2021). "Both FGF1 and FGF2 promote glucose uptake by human prostate cancer cells and mouse adipocytes through the MEK/ERK pathway." (PMID 39433211, 2025). "These mtDNA mutations increase the secretion and expression of fibroblast growth factor 1 (FGF-1) and focal adhesion kinase (FAK) to promote prostate cancer bone metastasis." (PMID 35454769, 2022). "KLK4 activated protease‐activated receptor‐1 in WPMY1 cells increasing expression of several factors (FGF1, TAGLN, LOX, IL8, VEGFA) involved in prostate cancer progression." (PMID 28510269, 2017). "In prostate cancer, FGFR1 and FGFR4 as well as the ligands FGF-1, FGF-2, FGF-6, FGF-8, FGF-9, and FGF-17 are all known to be over-expressed." (PMID 22078327, 2011). "Previously, it has been reported that FGF-1 stimulation leads to the activation of ERK1/2, which in turn phosphorylates STAT3 at Ser727 in prostate cancer cells." (PMID 21906308, 2011). "FGFR3 binds to multiple FGFs known to be upregulated in human prostate cancer (FGF1, FGF2 and FGF8), and is potentially important in prostate cancer." (PMID 15655558, 2005). "Similarly, inhibition of both FGF1 and FGF2 decreases the LDHA/LDHB ratio in prostate cancer cells through the transcription factor STAT1." (PMID 39433211, 2025). "Similarly, inhibition of both FGF1 and FGF2 decreases lactate production, as well as the basal and maximal ECAR in prostate cancer cells." (PMID 39433211, 2025). "However, the specific mechanism through which FGF1 and FGF2 regulate aerobic glycolysis in prostate cancer remains unclear." (PMID 38764020, 2024). "Previous studies showed the capability of 3-hydroxytyrosol and chlorogenic acid to reduce BCL-2 and caspase-3 gene and protein expression, respectively, while gentisic acid could interact with fibroblast growth factor 1 (FGF1), whose levels are increased in prostate cancer." (PMID 36234818, 2022).
melanoma (13 papers, 2012 to 2025). A malignant, usually aggressive tumor composed of atypical, neoplastic melanocytes. "In line with this interpretation, excessive angiogenesis, a hallmark of melanoma, and the progression from a radial growth phase to a vertical growth phase has been shown to require high angiogenic activity dependent on FGF1, FGF2 and VEGFA." (PMID 29666124, 2018). "Among the up-regulated oncogenes in melanoma, ABL2, NRAS, PDGFC and FGF1 have been reported to be melanoma-associated oncogenes." (PMID 22295108, 2012). "Evidence showed that melanoma cells (A375) released fibroblast growth factor (FGF)-1 and FGF-2 and this process required copper ions by activation of phosphati-dylinositol 3-kinase (PI3K)/Akt pathway." (PMID 37004045, 2023). "This implies that FGF1 is most likely the relevant factor, which impacts melanoma cells as well as fibroblasts." (PMID 30237393, 2018). "As FGFs are potent growth factors with multiple effects on different cell types of the melanoma microenvironment, we were interested to investigate if other FGFs are induced by BRAF inhibition in melanoma cells in addition to FGF1." (PMID 30237393, 2018). "Together, FGF1 has beneficial effects on melanoma cells and fibroblasts, thereby limiting the efficacy of BRAF inhibition." (PMID 30237393, 2018). "Melanoma-induced gap formation between endothelial cells was significantly reduced for FGF-1 treated monolayers in comparison to controls." (PMID 28393886, 2017). "In primary tumours of human melanoma patients, the expression of both FGF1 and FGF2 mRNA displayed a significant positive correlation with the expression of down-stream targets of the ATF6 and PERK branches of the UPR." (PMID 29235576, 2017). "As ASA-induced effects were blocked by modulation of SOX2 by PGF2α and FGF-1 in melanoma cells, we next investigated if PGF2α-FP receptor antagonist, AL8810 can mimic ASA effects and if SOX-2 upregulation can abrogate its effect?" (PMID 28636992, 2017). "In our study, treatment with FGF-1 to lock VE-cadherin homodimers at cell-cell junctions prevented melanoma-mediated gap formation in endothelial monolayers." (PMID 28393886, 2017). "Both PGF2α and FGF-1 significantly attenuated AL8810-induced reduced survival of melanoma cells similar to as seen with ASA-treatment." (PMID 28636992, 2017). "Our data show that the UPR in metastatic melanoma cells contributes to increased FGF1 and FGF2 expression and enhances cell migration." (PMID 29235576, 2017). "Monolayers of HPMECs were treated with FGF-1 for 1 hour, gently rinsed, and then immediately co-cultured in direct contact with A2058 melanoma cells for 0, 10, 45, or 90 min." (PMID 28393886, 2017). "To test whether FGF1 affects the sensitivity of melanoma cells to BRAF inhibition, we treated the melanoma cell lines M14, UACC-62, and A375 for 5 days with 2 μM vemurafenib in absence or presence of AZD4547, FGF1 or a combination of both." (PMID 30237393, 2018). "We show here that neutrophils responding to early melanoma onset may provide an early source of Fgf1 and Fgf6." (PMID 29666124, 2018). "FGF1 could limit the inhibitory effect of vemurafenib on melanoma cells, while the simultaneous inhibition of BRAF and FGF receptors increased the anti-tumorigenic effect." (PMID 30237393, 2018). "Moreover, PGF2α-receptor antagonist, AL8810 mimics ASA-induced decreased melanoma cells survival which was significantly blocked by PGF2α and FGF-1." (PMID 28636992, 2017). "Importantly, SOX2 upregulation by FGF-1 promoted the survival of melanoma cells and significantly blocked ASA-induced reduced cell survival and increased apoptosis." (PMID 28636992, 2017). "We first tested if the same dosing regimen (10ng/ml) of FGF-1 at 24 hour could induce SOX2 in melanoma cells?" (PMID 28636992, 2017). "Interestingly, modulation of SOX2 expression by PGF2α agonists and upregulation by fibroblast growth factor 1 (FGF-1) rescued melanoma cells from ASA-induced decreased survival and increased apoptosis." (PMID 28636992, 2017).
melanoma (continued). "Additionally, fibroblast growth factor 1 (FGF1) inhibitors have been studied in this context, as the upregulation of FGF1 has been implicated in resistance to BRAF and MEK inhibition, and its blockade may help to resensitize melanoma cells to targeted therapy." (PMID 40508177, 2025). "Consistently, the FGF genes FGF1 and FGF2 are highly expressed in CAF cells in the melanoma tissue from female patients." (PMID 35134150, 2022). "Taken together, the UPR regulates FGF1 and FGF2 expression in human melanoma and reduction of the UPR using a chemical chaperone reduces cell viability and invasion." (PMID 29235576, 2017). "Our next studies determined if PGF2α and FGF-1 that modulate SOX2 expression, can rescue melanoma cells from AL8810-induced inhibition of survival, and compared the responses with ASA." (PMID 28636992, 2017). "On the other hand CYT-low metastatic melanomas had recurrent amplifications in loci 5p15.33 (TERT), 6p25.1 (CDYL), 7p22.2 (RAC1), 12q15 (MDM1) and recurrent deletions in 5q31.2 (CTNNA1, FGF1), 11q22.3 (FDX1, RDX, ZC3H12C), and 15q14 (RASGRP1, CSNK1A1P1, SPRED1)." (PMID 33779796, 2021). "Microarray and GSEA data were validated by examining FGF1 and FGF2 expression in non-metastatic and metastatic melanoma cells after 4-PBA treatment." (PMID 29235576, 2017).
asthma (12 papers, 2020 to 2024). "A mouse model of asthma induced by ovalbumin and miR-370 carried by M2 macrophage-derived exosomes alleviated asthma progression by inhibiting the FGF1 and MAPK/STAT1 signaling pathways." (PMID 35884901, 2022). "A recent study reported that M2 macrophage-derived exosomes (M2Φ-Exos) carried miR-370 to mitigate asthma progression via restraining the FGF1/MAPK/STAT1 signaling axis." (PMID 35500231, 2022). "Previous studies reported that M2Φ-Exos carried miR-370 to inhibit inflammation and alleviate asthma progression by regulating the FGF1/MAPK/STAT1 axis." (PMID 35500231, 2022). "Previous study has confirmed that the increasing number of proteins have been validated to exert role in asthma, for example, FGF1 accelerates the proliferation and migration of airway smooth muscle cells in asthma." (PMID 34876240, 2021). "Downregulation of miR-370 by Lv-miR-370 inhibitor or overexpression of FGF1 by Lv-FGF1 blocked the protective roles of M2Φ-Exos in asthma-like mouse and cell models." (PMID 33994863, 2021). "Collectively, we conclude that M2Φ-Exos carry miR-370 to alleviate asthma progression through downregulating FGF1 expression and the MAPK/STAT1 signaling pathway." (PMID 33994863, 2021). "Herein, this study was carried out to explore whether M2Φ-exosomal miR-370 alleviated asthma progression via inhibiting the expression of FGF1, and an OVA-induced mouse model and PDGF-treated ASMCs model were used to validate this hypothesis." (PMID 33994863, 2021). "In the ovalbumin (OVA)-elicited asthmatic rat model, M2 macrophage exosome miR-370 lowers FGF1 expression and down-regulates the MAPK/STAT1 signaling pathway to alleviate lung tissue fibrosis and inflammation, thus ameliorating asthma." (PMID 37142272, 2023). "A previous study noted that FGF1 played important roles in the progression of idiopathic pulmonary fibrosis through activating the MAPK signaling pathway 23, which attracted our attention that whether this signaling pathway is also implicated in asthma development." (PMID 33994863, 2021). "TUG1, serving as the molecular sponge of miR-138-5p, miR-590-5p, miR-216a-3p, and miR-181b, has been confirmed to be involved in ASMC proliferation and migration in human asthma by modulating E2F transcription factor 3 (E2F3), fibroblast growth factor 1 (FGF1), Smurf2 and HMGB1, respectively." (PMID 35769905, 2022). "Interestingly, FGF1 upregulation by the lncRNA TUG1/miR-590-5p axis was found to accelerate proliferation and migration of airway smooth muscle cells and the consequent asthma development." (PMID 33994863, 2021).
colorectal cancer (12 papers, 2019 to 2025). A primary or metastatic malignant neoplasm that affects the colon or rectum. "Additionally, it has been shown that loss of AKR1B10 promotes the proliferation and migration of colorectal cancer cells via activation of fibroblast growth factor 1 (FGF1)." (PMID 35204145, 2022). "In this study, FGF1 expression was significantly higher in colorectal cancer than in normal tissues by detecting 135 normal and paired CRC tissues." (PMID 34552869, 2021). "TCGA dataset analysis by GEPIA platform showed that the expression of FGF1 in colorectal cancer tissues was positively correlated with S6K1." (PMID 34552869, 2021). "Meanwhile, down-regulation of FGF1 expression can effectively inhibit the proliferation and migration ability of colorectal cancer cells in vitro." (PMID 34552869, 2021). "To gain further mechanistic insights, we examined the knockdown effect of FGF1 in colorectal cancer cells firstly." (PMID 34552869, 2021). "FGF1 enhances the tumorigenicity and proliferation of colorectal cancer cells." (PMID 38764020, 2024). "We also showed that we can customize the SmiRNPs by switching the EGF ligand to either FGF1 or VEGF‐A, which also showed gene silencing efficacies in two different cancer cell types (colorectal carcinoma and pancreatic ductal adenocarcinoma)." (PMID 40702844, 2025). "However, the expression level and role of FGF1 in colorectal cancer remain unclear." (PMID 34552869, 2021). "PHF20L1 promotes EMT of colorectal cancer cells and increases their invasiveness and metastatic abilities; it also regulates the expression of various angiogenic factors (such as ANGPT2, FGF1, PDGFA, and VEGFA) and promotes angiogenesis in colorectal cancer tissues." (PMID 40723918, 2025). "A recent study showed that FGF-1/-3/FGFR4 signaling in CAF promotes tumor progression in colon cancer through ERK and MMP-7, inducing angiogenesis and cell proliferation, which suggests a crucial role of CAF and FGF signaling in colorectal cancer." (PMID 33946534, 2021).
diabetic nephropathy (12 papers, 2018 to 2025). "FGF-1 has been shown to reduce oxidative stress and endoplasmic reticulum (ER) stress in diabetic nephropathy." (PMID 38542166, 2024). "FGF-1 mitigates oxidative stress, preventing diabetic cardiomyopathy, kidney cell stress in diabetic nephropathy, and cellular stress in DM-induced liver injury." (PMID 38542166, 2024). "FGF1 has been reported to ameliorate diabetic nephropathy by an anti-inflammatory and antioxidant stress-induced mechanism." (PMID 35883655, 2022). "It has been reported that FGF1 ameliorates diabetic nephropathy through exerting its anti‐inflammatory function and suppressing the cellular stress in kidney." (PMID 33788387, 2021). "Additionally, FGF-1 has shown efficacy in preventing diabetic nephropathy by mitigating renal inflammation with a reduction in nuclear factor κB and c-Jun N-terminal kinase signaling pathways and via the PI3K/AKT pathway in different studies." (PMID 38542166, 2024). "Based on the results of transcriptomics, the pathogenesis of diabetic kidney disease may involve 11 candidate differential genes: Egr1, Foxo3, Pik3r3, Fgf1, Sost, Wnt10a, Tgif2, Akt2, Mep1b, Col1a1, Apoe." (PMID 36249745, 2022). "For instance, FGF1 has been previously shown to inhibit the NF-κB pathway in experimental diabetic nephropathy, whereas GDF15–mediated inhibition of NF-κB signalling reduces infiltration of macrophages and arrests the pro-apoptotic activity in early tumour development." (PMID 35883655, 2022). "Fibroblast growth factor 1 (FGF1) protects renal function against diabetic nephropathy (DN)." (PMID 34149434, 2021). "FGF1 significantly prevented the development of nonalcoholic fatty liver disease (NAFLD) and diabetic nephropathy (DN)." (PMID 39199276, 2024). "Importantly, FGF1 was shown to exert protective effects against oxidative stress and inflammation in various disease models, including spinal cord injury and diabetic nephropathy, via activation of Nrf2- mediated antioxidant defense and suppression of NF-κB activation, respectively." (PMID 35764933, 2022).